WT1 (WT1 transcription factor)
Diseases named in the same sentence as WT1 in open-access papers (continued):
Sharing a sentence is not in itself a finding about the gene and the disease.
cancer (continued). "Furthermore, CDW secreted IL-12 and IFN-γ, which induced the differentiation of naïve T cells to active CD8+ T cells and elicited cytotoxic T lymphocyte (CTL) response against cancer cells with WT1 antigens." (PMID 36675017, 2023). "Our clinical study on rare cancers showed that the biweekly WT1 Trio peptide vaccine comprising two WT1-cytotoxic T lymphocyte (CTL)-peptides and one WT1-helper T lymphocyte-peptide induced more robust immune responses targeting WT1 than the weekly WT1-CTL peptide (WT1-235) vaccine." (PMID 36672344, 2023). "This suggests that cytotoxic T lymphocytes alone are insufficient for robust anti-cancer activity, which may explain the limitations of WT1 peptide-based therapeutic cancer vaccine containing only CD8+ T-cell epitopes." (PMID 36138335, 2023). "Wilms tumor 1 (WT1) is a promising target antigen for cancer immunotherapy." (PMID 36760714, 2023). "The present study demonstrates the importance of DTH in cancer treatment with WT1-DC." (PMID 38143707, 2023). "This second cluster could represent a cancer-associated fibroblast (CAF) population characterized by low expression of MSLN and WT1 and high expression of ACTA2, S100A4, COL5A2, SPARC, and FN1." (PMID 36901697, 2023). "Therefore, the antitumor activity of WT1-based therapeutic cancer vaccines will likely be maximized by the inclusion of epitope sequences that stimulate both cytotoxic and helper T cells." (PMID 36138335, 2023). "Studies revealed the multi-faceted function of Wilms’ tumor (Wt1) genes in cancer, which may be related to the existence of multiple alternative splices." (PMID 36829196, 2023). "WT1, which is overexpressed in most adult and pediatric patients with acute leukemia, chronic myelocyte leukemia, and myelodysplastic syndrome, is considered most promising among 75 TAAs as a target for cancer vaccines and/or T cell adaptive immunotherapy." (PMID 35699757, 2023). "The role of PAWR (Pro-Apoptotic WT1 Regulator) in cancer remains unknown and its antiproliferative activity might be due to its anti-apoptosis function." (PMID 37414763, 2023). "The WT1 has been reported to be overexpressed in a variety of tumors, including leukemia, breast cancer, and pediatric kidney tumors (Wilms' tumor) and to play an oncogenic role in other cancer types including renal and bladder cancer." (PMID 37340017, 2023). "Since all WT1-expressing tumors are targets of WT1-specific CTLs, WT1 may be a common target antigen for rare cancers, and WT1-targeting immunotherapy could be applied to rare cancers expressing WT1." (PMID 36672344, 2023). "Considering the relatively low oxygen tensions in rapidly growing tumors, it would be reasonable to speculate that intratumoral hypoxia could lead to enhanced HIF expression, which transcriptionally activates WT1 in these cancers." (PMID 35465313, 2022). "Therefore, a combination of the positive and negative markers, including at least two mesothelial cell markers (D2-40, calretinin, WT1) and two cancer cell markers (TTF-1, CEA, polyclonal, claudin-4), is recommended for the diagnosis of DMPM." (PMID 36684194, 2022). "As the relative expression fold of WT1 can be considered a marker for cancer progression, decreasing its expression may, therefore, play a role in stabilizing the disease status in CML cases." (PMID 36078884, 2022). "Compared with normal human tissues, WT1 is expressed at a rather high level in various malignancies including ovarian, breast, uterine, lung, colon cancers and malignant pleural mesothelioma." (PMID 35465313, 2022). "They developed a recombinant BL that contains Wilms’ tumor 1 (WT1) protein as a cancer vaccine." (PMID 35892683, 2022). "In addition, to facilitate the long-term use of HIF–PHIs in anemic CKD patients, we will discuss the strategy of WT1 inhibition to reduce the development and progression of cancer." (PMID 35465313, 2022).
cancer (continued). "Thus, in a liquid immune suppressive microenvironment, both WT1-expressing EpCAM+ adenocarcinoma cells and WT1-CTLs reflected cancer progression." (PMID 36293034, 2022). "Currently, the functions of wt1 in cancers are thought to depend on the cell and tissue types." (PMID 36412640, 2022). "The WT1 peptide is present in most cancer patients expressing HLA A*02." (PMID 36338746, 2022). "WT1 is an ideal target for cancer immunotherapy due to its limited expression on healthy tissues." (PMID 35356211, 2022). "We identified the WT1 expression of the EpCAM+ cancer cells observed in MPE samples." (PMID 36293034, 2022). "Taken together, miR-642a-5p replacement in 22Rv1 and LNCaP PCa cells with ectopic overexpression of WT1 significantly ‘rescues’ its anti-cancer effects on WT1 gene targeting, further suggesting miR-642a-5p could be an ideal therapy in PCa." (PMID 34504167, 2021). "In addition, studies have shown that WT1 can influence the progression of cancer through a variety of genes or signaling pathways." (PMID 34692659, 2021). "The WT1 cancer epitope RMFPNAPYL presented by HLA-A*0201 is targeted by the TCRm mAb ESK1." (PMID 33836029, 2021). "This WT1 oral cancer vaccine alone or as an adjunct to anti-PD-1 antibody could provide a novel treatment option for patients with advanced urothelial cancer." (PMID 34589578, 2021). "Recently, it has been reported that Wilms tumor gene 1 (WT-1) may assist in the distinction of OSCs and USCs, since WT-1 staining patterns differ between these two carcinomas." (PMID 34187525, 2021). "WT1-DC vaccination for patients with cancer demonstrated the safety and immunogenicity in vivo." (PMID 32231023, 2020). "Moreover, we noted that WT1 showed higher rates of expression in advance FIGO staged cancers (33%) in all histotypes." (PMID 32859123, 2020). "In another study, WT1 peptide-pulsed DC vaccination was used to treat advanced cancer patients." (PMID 32210734, 2020). "Wilms’ tumor 1 (WT1) molecules are expressed in various types of solid tumors; therefore, a peptide vaccination targeting this molecule has priority as an immunotherapy for cancer patients." (PMID 32231023, 2020). "Administration of WT1-DCs with OK-432 might be essential for achieving sufficient induction of functional WT1-CTLs in patients with cancer." (PMID 32231023, 2020). "Furthermore, immune monitoring of WT1-CTLs as practical application of the total process including shipping of the WT1-DC vaccine after WT1-DC-administration demonstrated that WT1-DCs induced WT1-CTLs in patients with cancer." (PMID 32231023, 2020). "Furthermore, we evaluated the induction of WT1-specific CTLs in cancer patients who received WT1-DC administration." (PMID 32231023, 2020). "Wilms tumor 1 (WT1) is a high-priority antigen target for cancer immunotherapy." (PMID 32793489, 2020). "Interestingly, WT1 was ranked as the top immunotherapy target in cancer by a national cancer institute pilot project for the prioritization of cancer antigens." (PMID 30897713, 2019). "Moreover, WT1 has been ranked at the top position in the National Cancer Institute's (NCI) list of cancer antigens with the highest prioritization for vaccine development." (PMID 31245293, 2019). "In contrast, knockdown of WT1 gene increased apoptosis of different cancer cell lines." (PMID 31245293, 2019). "Targeting intracellular antigens such as Wilms Tumor 1 (WT1) in cancer could provide a new road to target antigen selection." (PMID 30108584, 2018). "The Wilms' tumor antigen 1 (WT1) has been shown to be highly expressed and plays an oncologic role in various hematological and solid malignancies, but is negligibly expressed in normal tissues, thus making WT1 an ideal target for cancer immunotherapy strategies." (PMID 30631324, 2018). "WT1 is a new gene with hypermethylation status in malignant tumors(Rauscher 3rd, 1993)." (PMID 29658966, 2018). "Vascular WT1 in cancers decreased as histopathological grade increased." (PMID 30374123, 2018).
cancer (continued). "The association between WT1 and HER2 status was assessed in 57 cancers." (PMID 30374123, 2018). "Hence, a commonly used TAA is the oncoprotein Wilms’ tumor-1 (WT1), which has been ranked the number one cancer vaccine target antigen." (PMID 29867960, 2018). "However, sub-analyses based on stratification of ER status demonstrated a higher WT1 expression in ER-positive than ER-negative cancers." (PMID 30374123, 2018). "For example, DUSP6 as a phosphatase, regulated phosphorylation of its downstream gene ERK1/2 to promote cell proliferation, and it may contribute to the relapse by crosstalk with WT1 through transcriptional misregulation in cancer pathway." (PMID 30195757, 2018). "Importantly, the anti-cancer activity induced by miR-193a was partially reversed by WT1 overexpression, indicating an important role for WT1 in such activity related to miR-193a." (PMID 29016617, 2017). "Overall, perturbing the expression levels of WT1 affects the epithelial/mesenchymal balance of cancer cells, but does not cause any significant change in cancer stem-cell properties, cell proliferation or apoptosis." (PMID 28345629, 2017). "Therefore, OCV-501 is an HLA class II- restricted WT1-helper peptide for therapeutic cancer vaccine." (PMID 28321480, 2017). "It is well known that inherited and acquired changes in pre-mRNA splicing play a significant role in human disease development and many cancer-associated genes are regulated by alternative splicing, such as CD44, the Wilms' tumor gene WT1, BRCA1, MDM2, FGFR and kallikrein family members." (PMID 29156833, 2017). "Thus, we intended contribute to decode the WT1 involvement in OS by a cancer cell line model that closely mimics the patient derived and WT1-positive OS." (PMID 28107196, 2017). "Wilms’ tumor 1 (WT1) antigen is acknowledged as a top-ranked among 75 cancer antigens." (PMID 28321480, 2017). "Although WT1 has been originally recognized as a tumor suppressor gene, some studies have demonstrated that its expression increased during development and progression of different human cancers, such as hematological malignancies and solid tumors." (PMID 27014421, 2016). "Importantly, knockdown of WT1 resembled the anti-cancer activity by miR-193a and overexpression of WT1 partially reversed miR-193a-induced anti-cancer activity, indicating that WT1 plays an important role in miR-193a-induced anti-cancer activity." (PMID 27821145, 2016). "Wilms’ tumor 1 (WT1) antigen-specific cytotoxic T cells were then evaluated by both the ELISpot assay and WT1 tetramer analysis in peripheral blood from 46 cancer patients who received DC vaccinations pulsed with human leukocyte antigen (HLA)-A*24:02-restricted modified WT1 peptides." (PMID 28536414, 2015). "Therefore, we evaluated WT1 antigen-specific CTLs (WT1-CTLs) using the IFN-γ ELISpot assay in comparison with the MHC tetramer analysis as a validation method of DC-based cancer immunotherapy." (PMID 28536414, 2015). "Ex4a(+)WT1 isoform expression in human cancer cells and normal kidney cells was examined." (PMID 26090994, 2015). "It has been shown that WT1 was overexpressed in a number of cancer cells, and more importantly, knockdown of WT1 by shRNA could induce mitochondrial damage and then inhibit malignant cell growth." (PMID 25748047, 2015). "Ex4a(+)WT1 isoform was detected in all the WT1-expressing cancer and normal kidney cell lines." (PMID 26090994, 2015). "Clinical trials have suggested the safety and clinical efficacy of WT1 immunotherapy in cancer." (PMID 25026998, 2014). "According to its criteria, WT1 ranked the highest out of 75 cancer antigens prioritized." (PMID 25026998, 2014). "Thus, in VHL-knockdown WT1-expressing cancer cells, markers of both EMT and MET coexisted, and these cells displayed epithelial-like morphology." (PMID 25025131, 2014). "In most of the samples, WT1 was detected in the cytoplasm as well as in the nuclei of cancer cells." (PMID 24810959, 2014).
cancer (continued). "However, over the years, it became apparent that WT1 is involved in the development of several other organ systems and that it can also be overexpressed in many different types of cancer consistent with the properties of a proto-oncogene." (PMID 24101931, 2013). "Recently, WT1 was ranked first in a list of 75 cancer antigens." (PMID 24228711, 2013). "The staining for Wilms’ tumor 1 protein (WT1) was positive in the nuclei of the cancer cells." (PMID 22747642, 2012). "• WT1 Peptide Vaccination in Carcinomas.• Prior treatment with EGFR inhibitor chemotherapy..." (PMID 23282337, 2012). "Notably, it has been repeatedly reported that immune responses against WT1 are naturally elicited in cancer patients, indicating that WT1 protein is immunogenic." (PMID 22028726, 2011). "Mesothelin, calretinin and WT-1 were expressed in almost all cancer cells." (PMID 21305058, 2011). "Although many factors are worth in-depth investigation we focus on the targets of two disease-relevant regulators: the targets of OCT4 and their relation to diabetes and, more extensively, the targets of WT1 and their relation to cancer development and progression." (PMID 18564415, 2008). "Considering that a tissue is heterogeneous in cell types, it is reasonable to assume that the Wt1 mRNA detected in LM was derived from stromal tissue whereas the cancer cells might have lost Wt1 expression." (PMID 18218118, 2008). "Benign prostate tissue expressed FGFR1 and WT1 less frequently than carcinoma samples." (PMID 17137506, 2006). "FGFR1, TACC1 and WT1 were overexpressed in HR LuCaP 23.1 carcinoma cells." (PMID 17137506, 2006). "However, the extent to which this data represented WT1-specific TCRs from cancer patients, which is crucial for monitoring and biomarker identification, remained unknown." (PMID 39259326, 2025). "Therefore, the combination therapy of WT1-DC and α-Galcer-DC may be useful even in highly malignant cancers." (PMID 39035592, 2024). "Therefore, since WT1 is widely overexpressed in rare cancers, WT1-targeted immunotherapy may be a therapeutic strategy for rare cancers." (PMID 36672344, 2023). "Therefore, WT1 has been used as one of the targets of immunotherapy for cancer." (PMID 36675017, 2023). "Therefore, we conclude that WT1-targeted immunotherapy may be a potential therapeutic strategy for rare cancers." (PMID 36672344, 2023). "In addition to monitoring, more research into WT1 inhibition in these cancers is required." (PMID 35465313, 2022). "In addition, vaccines or drugs currently developed targeting WT1 have been used in cancer treatment, and some of them may be combined with conventional chemotherapy or other drugs to treat cancer." (PMID 34692659, 2021). "Moreover, the prognostic value of WT1 alteration in some cancer was demonstrated." (PMID 33110919, 2020). "However, whether inhibiting deubiquitination of WT1 facilitates its degradation and presents anti‐cancer ability in PDAC is unknown." (PMID 31845546, 2020). "Therefore, selecting effective agents which can rapidly degrade WT1 might provide a potentially attractive approach to cancer therapy." (PMID 31845546, 2020). "WT1 may function either as a tumor suppressor or an oncogene depending on the type of cancer." (PMID 31245293, 2019). "A TCR-mimic antibody targeting a Wilms tumor 1 (WT1) peptide in the context of HLA-A2 has demonstrated efficacy in preclinical models; however, the ability to specifically target MANAs is critical to make these strategies applicable to a wide range of cancer patients." (PMID 31690625, 2019). "Thus, elucidating the complex regulatory net of WT1 by miRNAs may shed light on the high expression of WT1 in cancer cells." (PMID 27821145, 2016). "However, the role of WT1 in cancer is complicated, with conflicting reports as to whether it has a tumor suppressive or oncogenic function." (PMID 26462627, 2015).
cancer (continued). "Furthermore, we wanted to determine whether WT1 IgG Ab level in plasma may relate to WT1 protein expression in cancer tissues specimens." (PMID 24715586, 2014). "In addition, a single exposure of cancer cells to TCPOBOP increased the expression of two tumor suppressor genes (WT1 and MGMT), which could corroborate the improved efficacy of paclitaxel in cancer cell lines." (PMID 24959746, 2014). "Similarly, in a Cancer and Leukemia Group B study, which included 196 adult AML patients from two clinical studies, WT1 mutation predicted a worse 3-year disease-free and OS compared to wild-type WT1 AML patients independently of CEBPA, FLT3-ITD, and NPM1 mutational status." (PMID 41102401, 2026). "In order to validate their usability on cancer TCR repertoires, the two models were utilized for the identification of WT1-126 and WT1-37 specific TCRs in cancer patients." (PMID 39259326, 2025). "Cancer vaccines represent another immunotherapeutic approach that is being explored for the treatment of BTC, with studies focusing on WT-1 and MUC1 antigens." (PMID 40940908, 2025). "In contrast, Wt1 is well established in the literature as an EMT driver in both developmental and cancer settings and was the most significant DEG (>24 fold-change) in the dataset." (PMID 38977895, 2024). "One possible reason for the marked shrinkage of the cancer, despite the discrepancy between DTH and temperature trends, is that α-Galcer-DC was used in combination with WT1-DC in this case." (PMID 39035592, 2024). "Among the different strategies applied to reverse chemoresistance, the use of shRNA has been considered, since this genetic tool can downregulate expression of genes like WT1, AMBRA1, Bcl‐xL, and PLK1 to eventually enhance the chemosensitivity of cancer cells." (PMID 38919334, 2024). "We identified BLK as a kinase upregulated not only by EWSR1::WT1, but also in DSRCT cancer stem cell-like (CSC) culture conditions." (PMID 39139449, 2024). "Subsequent administration of seven doses of dendritic cell vaccine recognizing Wilms' tumor 1 (WT1) and α-galactosylceramide antigens resulted in significant shrinkage of the cancer and marked improvement of the patient's general condition." (PMID 39035592, 2024). "LEF1, WT1 and BCL11B copy number abnormalities were reported from the TARGET study of 2471 pediatric cancer patients whereas in our group we found CDKN2A, CDKN2B and MTAP harboring most copy number variations." (PMID 38459434, 2024). "Therefore, the WT1 mRNA and protein may act as promising targets for cancer therapy." (PMID 38742454, 2024). "In carcinoma ex pleomorphic adenoma, peptide-based WT1-targeting vaccines increased CD8+ T cells recognizing the WT1-derived peptide." (PMID 38539539, 2024). "Since IPS is a prognostic factor in advanced cancer, the magnitude of DTH due to WT1-DC inoculation is a useful indicator to estimate the patient's prognosis." (PMID 38143707, 2023). "WT1-specific CD8+ and CD4+ T cells activated by the HLA-antigen complex then migrate to the TME, where they attack WT1-positive cancer cells and exhibit an antitumor effect." (PMID 36138335, 2023). "Therefore, WT1-targeted immunotherapy may be a potential therapeutic strategy for rare cancers." (PMID 36672344, 2023). "WT1, minor histocompatibility A (HA)-1, telomerase (TERT), and survivin, neoantigens, and cancer-testis antigens (CTAs) have been reported as TAAs and have been explored in preclinical trials." (PMID 35356211, 2022).